BBS5 (Bardet-Biedl syndrome 5)
Description:
The BBSome complex is thought to function as a coat complex required for sorting of specific membrane proteins to the primary cilia. The BBSome complex is required for ciliogenesis but is dispensable for centriolar satellite function. This ciliogenic function is mediated in part by the Rab8 GDP/GTP exchange factor, which localizes to the basal body and contacts the BBSome. Rab8(GTP) enters the primary cilium and promotes extension of the ciliary membrane. Firstly the BBSome associates with the ciliary membrane and binds to RAB3IP/Rabin8, the guanosyl exchange factor (GEF) for Rab8 and then the Rab8-GTP localizes to the cilium and promotes docking and fusion of carrier vesicles to the base of the ciliary membrane. The BBSome complex, together with the LTZL1, controls SMO ciliary trafficking and contributes to the sonic hedgehog (SHH) pathway regulation. Required for BBSome complex ciliary localization but not for the proper complex assembly.
Synonyms: DKFZp762I194
Tractability: Antibody: its Gene Ontology location is reachable by antibodies, with medium confidence. PROTAC: ubiquitination databases record sites on it.
Gene: Protein-coding gene on chromosome 2 (169,479,480 to 169,506,655, forward strand). Ensembl gene ENSG00000163093.
Subcellular location: Cell projection, cilium membrane; Cytoplasm; Cytoplasm, cytoskeleton, cilium basal body; Cytoplasm, cytoskeleton, microtubule organizing center, centrosome, centriolar satellite
Subcellular location (Human Protein Atlas): Acrosome; Basal body; Cytosol; Perinuclear theca; Primary cilium
Pathways (Reactome):
Organelle biogenesis and maintenance: BBSome-mediated cargo-targeting to cilium
Gene Ontology:
Molecular function: phosphatidylinositol-3-phosphate binding; protein binding; RNA polymerase II-specific DNA-binding transcription factor binding
Biological process: cilium assembly; heart looping; melanosome transport; motile cilium assembly
Cellular component: BBSome; ciliary membrane; cilium; cytosol; ciliary basal body; axoneme; centriolar satellite; cytoplasm
Genetic constraint (gnomAD): Loss-of-function variants: 19 observed, 31.53 expected, observed/expected ratio (o/e) 0.6, 90% interval 0.42 to 0.88. The upper end of that interval is the gene's LOEUF score, 0.88, which puts it in group 3 of 6, group 1 being the genes least tolerant of losing a copy. Missense variants: 232 observed, 278.18 expected, observed/expected ratio (o/e) 0.83, 90% interval 0.75 to 0.93. Synonymous variants: 88 observed, 94.53 expected, observed/expected ratio (o/e) 0.93, 90% interval 0.78 to 1.11.
Homologues: Orthologues: chimpanzee BBS5 (100% identical), dog BBS5 (98% identical), pig BBS5 (98% identical), mouse Bbs5 (96% identical), rabbit BBS5 (96% identical), guinea pig BBS5 (94% identical), tropical clawed frog bbs5 (91% identical), zebrafish bbs5 (90% identical), Drosophila melanogaster BBS5 (47% identical), Caenorhabditis elegans bbs-5 (46% identical).
Diseases named in the same sentence as BBS5 in open-access papers:
BBS5 is named in the same sentence as 26 diseases in open-access papers, as found by Europe PMC text mining. Sharing a sentence is not in itself a finding about the gene and the disease. The quoted sentences say what the papers report.
ciliopathies (12 papers, 2014 to 2025). "We conclude that this novel BBS5 mutation has a deleterious function that accounts for the multisystem ciliopathy phenotype seen in affected human patients." (PMID 24559376, 2014). "One of these candidate genes, Bardet-Biedl syndrome 5 (BBS5), is associated with a rare ciliopathy that strongly predisposes individuals to diabetes and other metabolic complications: obesity and diabetes mellitus are actually considered diagnostic features of the disease." (PMID 31557856, 2019). "Thus, like in other ciliopathy models, ablation of Bbs5 led to aberrant pancreatic morphology, defective insulin signaling, and impaired glucose homeostasis." (PMID 40233116, 2025). "The TES analysis of the 21 previously reported ciliopathy genes associated with BBS resulted in the identification of a novel synonymous variant c.534A > G; p.(Q178Q) in ARL6 in family F01, and a novel 11 bp deletion c.734_744del; p.(E245Gfs*18) in BBS5 in families F02 and F03." (PMID 27708425, 2016). "Consistent with the link to diabetes progression in ciliopathy, and the higher diabetes prevalence in patients with BBS patients compared with control individuals with obesity, Bbs5–/– mice exhibited impaired glucose clearance." (PMID 40233116, 2025). "By elucidating the molecular pathways governed by BBS5, we aim to uncover potential therapeutic targets for treating BBS and related ciliopathies." (PMID 40233116, 2025).
Bardet-Biedl syndrome (7 papers, 2008 to 2024). A ciliopathy with multisystem involvement. "In considering the known causes of Bardet-Biedl syndrome associated with defects in BBS5, most of the disease-causing mutations are associated with the first six exons or introns of BBS5, and these would thus not selectively impact the BBS5L variant." (PMID 26867008, 2016). "Our observation of a retina-specific splice variant for Bbs5 is not unique amongst the Bardet-Biedl syndrome-causing genes." (PMID 26867008, 2016). "Bardet–Biedl syndrome (BBS) was classified as a ciliopathy in 2003, and eight of the highly conserved BBS proteins (BBS1, BBS2, BBS4, BBS5, BBS7, BBS8, BBS9, and BBIP10) establish a stable protein complex called the BBSome that undergoes IFT." (PMID 37208194, 2023).
Obesity (5 papers, 2010 to 2025). Accumulation of substantial excess body fat. "We investigated the mechanisms underlying BBS-induced obesity using a Bbs5-knockout (Bbs5–/–) mouse model." (PMID 40233116, 2025). "To elucidate the molecular underpinnings of BBS-associated hyperphagia and weight gain, we performed bulk RNA-Seq on the hypothalamus of 5-week-old (pre-obesity) and 12-week-old (post-obesity) Bbs5–/– mice." (PMID 40233116, 2025). "In the absence of a weight-matched comparator, it is challenging to disentangle the specific contribution of the Bbs5 gene deletion over and above the impact of obesity." (PMID 40519161, 2025). "Differential gene expression analysis revealed significant alterations in genes associated with primary cilia function at both the pre- and post-obesity stages in Bbs5–/– mice." (PMID 40233116, 2025). "When the obesity causal genes were overlapped with the fasted and fed networks, 7 genes (ADA, BBS5, CBL, CCND3, FASN, FTO and SCARB1) overlapped with PER1's downstream genes in the fed network (Fisher's Exact Test p-value = 0.037)." (PMID 20168994, 2010). "Given that obesity is a hallmark of BBS and a significant driver of its associated comorbidities, a deepening understanding of BBS5’s role in metabolism could yield critical insights into disease pathogenesis." (PMID 40233116, 2025). "However, obesity and metabolic dysfunction are described in case reports of most but not all patients with BBS5 mutations." (PMID 40519161, 2025). "Importantly, the gene expression changes observed in Bbs5–/– mice are not replicated in mice with prolonged high-fat diet exposure or obesity, suggesting that the effects are due to Bbs5 knockout rather than a secondary response to the metabolic changes." (PMID 40233116, 2025).
retinal degeneration (3 papers, 2019 to 2025). Degeneration of the retina. "Bbs5–/– mice exhibit significant visual impairments due to retinal degeneration, including a complete loss of cone photoreceptor function and reduced rod function, as evidenced by structural abnormalities in the outer nuclear layer and mislocalization of photoreceptor proteins." (PMID 40233116, 2025).
cone-rod dystrophy (2 papers, 2015 to 2022). Inherited retinal dystrophies that belong to the group of pigmentary retinopathies. "Patient 1 (p.R89X mutation and IVS7-27 T>G in the BBS5 gene), a 20-year-old man, had mental retardation (MiniMental State Examination 23; normal >24), rod-cone dystrophy, central obesity (height 158 cm, body weight 63 kg, body-mass index 25.2), and hypogonadism since the age of 5 years." (PMID 26325687, 2015). "Additionally, a mouse knockout model of BBS5 developed a cone-rod dystrophy as well as displayed mislocalization of cone-specific proteins such as OPN1SW, OPN1MW and GNAT2; we report that OPN1MW and GNAT2 are mislocalized in Bbs10−/− mice." (PMID 36125046, 2022).
developmental delay (1 paper, 2025). "Another male patient carried biallelic variants in BBS5, presenting with polydactyly, developmental delay, and ASD." (PMID 40558542, 2025).
esophageal SCC (1 paper, 2011). "Reverse transcription followed by quantitative PCR analysis showed that the mRNA expression levels of ECSA-1, -2 and -3 and FAM119A but not of HCA25a, GOSR1 and BBS5 were frequently elevated in esophageal SCC tissues." (PMID 21696638, 2011).
Horseshoe kidney (1 paper, 2014). A connection of the right and left kidney by an isthmus of functioning renal parenchyma or fibrous tissue that crosses the midline. "Renal anomalies may be structural changes such as renal parenchymal cysts, calyceal clubbing, foetal lobulation, dysplastic kidneys, unilateral agenesis, hydronephrosis and horseshoe kidney implicating BBS5 in normal renal development." (PMID 24559376, 2014).
Insulin resistance (1 paper, 2025). Increased resistance towards insulin, that is, diminished effectiveness of insulin in reducing blood glucose levels. "Elevated levels of key hormones observed in untreated Bbs5–/– mice reflected significant metabolic disruptions consistent with insulin resistance, hyperleptinemia, and altered satiety signaling." (PMID 40233116, 2025).
retinal disease (1 paper, 2016). "We did not evaluate the expression of several retinal disease-related genes such as UNC119 and BBS5 because of their strong expression in primary PBMCs or their ubiquitous expression in other regions besides the retina." (PMID 27170256, 2016).
cancer (2 papers, 2019 to 2022). A tumor composed of atypical neoplastic, often pleomorphic cells that invade other tissues. "The most highly connected gene, BBS5(Bardet-Biedl syndrome 5) has not been fully characterized, and its role in cancers not been well studied." (PMID 31117943, 2019).
metabolic disease (1 paper, 2025). A congenital disorder (due to inherited enzyme abnormality) or acquired (due to failure of a metabolically important organ) disorder resulting from an abnormal metabolic process. "To investigate the specific role of BBS5 in metabolic disease, we used a Bbs5–/– mouse maintained on a homogeneous C57BL/6J background born from heterozygous parents." (PMID 40233116, 2025).
BBS5 also shares sentences with these, for which no sentence is quoted: diabetes (2 papers); Usher syndrome (2); Alstrom syndrome (1); Arts syndrome (1); central obesity (1); genetic disease (1); hydronephrosis (1); hypogonadism (1); Mucopolysaccharidosis type IIIC (1); neurological disorders (1); polydactyly (1); retinal ciliopathy (1); Usher type 2A syndrome (1); Wolfram-like syndrome (1).